DUSP26 (dual specificity phosphatase 26)
Diseases named in the same sentence as DUSP26 in open-access papers (continued):
Sharing a sentence is not in itself a finding about the gene and the disease.
viral infection (1 paper, 2025). "Both DUSP26 and APBB2 were downregulated in the MSCs of SRLV-SP goats, suggesting a potential co-regulation in response to viral infection and inflammation." (PMID 40733561, 2025). "Thus, reduced expression of both DUSP26 and APBB2 could potentially amplify dysregulation in APP trafficking, oxidative stress, and cell death signaling in response to viral infection or hypoxia-related stress." (PMID 40733561, 2025).
tumor (18 papers, 2014 to 2025). "DUSP26 is heavily implicated in cancer where, akin to other DUSPs, it displays both tumour-suppressive and -promoting properties, depending on the context." (PMID 33466673, 2021). "DUSP26 activity leads to increased chemoresistance to doxorubicin and VP-16 (etoposide) treatment, and overexpression was seen in high-risk NB tumor tissue samples correlating with a worse prognosis in these patients." (PMID 26247726, 2015). "Recently, studies have demonstrated that FADD plays a crucial role in cell growth by interacting with the adenylate kinase 2 (AK2)/dual-specificity phosphatase 26 (DUSP26) protein complex and could be associated with tumor cell differentiation." (PMID 27764170, 2016). "In the GBM tissue microarray, we found that DUSP26 was mainly expressed in the nuclei of tumor cells, and the expression of DUSP26 correlates with Ki67 staining in GBM." (PMID 33718185, 2021). "Collectively, our findings suggest that the anti-tumor effects of DUSP26 are manifested through regulation of tumor cell proliferation/migration, apoptosis, and senescence via modulating YAP/ERK, Akt/AMPK and/or p38/STAT1 signaling pathways." (PMID 33718185, 2021). "OPCs, which were throughout the tumor region, had varied DUSP26 expression based on their location within the tumor." (PMID 33718185, 2021). "One study demonstrated that DUSP26 mRNA was downregulated in NB cell lines compared to normal adrenal tissue, implicating DUSP26 as a potential tumour suppressor." (PMID 33466673, 2021). "It would be necessary to further define the oncogenic or tumor suppressive functions of DUSP26 in human NB before pointing to DUSP26 as a target for inhibition in these types of cancers." (PMID 30866462, 2019). "Consistent with a role as tumor suppressor, DUSP26 is down-regulated, in several human cancer cell lines, as well as in some primary tumors." (PMID 24847354, 2014). "We, therefore, propose that AK2 is a negative regulator of tumour growth that activates DUSP26 to suppress cell proliferation by FADD in human cancers." (PMID 24548998, 2014). "Furthermore, observations that DUSP26 overexpression inhibits tumor cell proliferation and migration, induce cell apoptosis, collectively highlight tumor suppressive role of DUSP26 in HGG." (PMID 33718185, 2021). "DUSP26 displays both tumour-suppressive and -promoting properties in different contexts." (PMID 33466673, 2021). "This is the first study that verifies the tumor suppressor role of DUSP26 in GBM." (PMID 33718185, 2021). "In contrast, DUSP26 surfaces as a tumour suppressor in the majority of other cancers." (PMID 33466673, 2021). "DUSP26 mRNA were significantly reduced in tumour specimens compared to normal brain tissue." (PMID 33466673, 2021). "Collectively, these findings indicate that DUSP26 might act as a tumor suppressor in GBMs, and suppression of activity or expression of DUSP26 might contribute to tumorigenesis of GBMs." (PMID 30791455, 2019). "In tumor cells, DUSP26 is known to act as both oncogene and tumor suppressor." (PMID 30791455, 2019).
tumor (continued). "On the other hand, DUSP26 seems to have oncogenic as well as tumor suppressor characteristics." (PMID 29682206, 2018). "After correction for age, tumor size, stage and grade, ER/PR/HER2 status and 3-gene classifier subtype, the loss of WRN (p=0.053; HR 1.2), DUSP26 (p=0.022; HR 1.3), UNC5D (p=0.026; HR 1.3), ZNF703 (p=0.026; HR 1.3) and FGFR1 (p=0.002; HR 1.5) still predicted worse DFS." (PMID 29682206, 2018). "Thus, it is presumable that the anti-tumor effect of DUSP26 overexpression may arise from inhibition of MAPK-ERK and YAP signaling pathway via dephosphorylation of ERK and YAP." (PMID 33718185, 2021). "In the current study, we found that high expression of DUSP26 has a direct impact on multiple signaling pathways, including MAP kinase and Akt pathways, suggesting that loss of DUSP26 expression is a crucial regulatory event associated with over activation of pro-tumor signaling in GBM cells." (PMID 33718185, 2021). "The anti-tumor effect of DUSP26 is associated with inhibition of MAPK and Akt signaling pathways that may arise from dephosphorylation of signaling proteins including, p38, STAT1, ERK, YAP, Akt, and AMPK, which are known substrate of DUSP26 enzymatic activity." (PMID 33718185, 2021). "Furthermore, the higher the histological grade of the tumour, the lower the DUSP26 protein levels." (PMID 33466673, 2021). "To assess DUSP26 expression levels in GBM versus normal brain tissue, we used the GEPIA database, which allows tumor/normal differential expression analysis." (PMID 33718185, 2021). "In summary, DUSP26 expression is down-regulated in neoplastic cells within GBM tissue, where non-tumor cells account for the bulk of DUSP26 expression." (PMID 33718185, 2021). "It was also shown that Adenylate kinase 2 (AK2) forms a complex with DUSP26 and stimulates the DUSP26 activity, resulting in the dephosphorylation of FADD and the regulation of tumor cell growth." (PMID 27583453, 2016). "In the present study, we show that AK2 forms a protein complex with DUSP26 and stimulates the phosphatase activity of DUSP26 resulting in the dephosphorylation of p-FADD and the regulation of tumour cell growth." (PMID 24548998, 2014). "Considering the great complexity of the tumour cell microenvironment in vivo, it is plausible that the molecular studies in vitro do not accurately represent the physiological function of DUSP26." (PMID 33466673, 2021). "Although only eight samples were analysed (four healthy and four T-LBL tumours), they demonstrated that DUSP26 protein was upregulated in three T-LBL tumours and none of the healthy controls." (PMID 33466673, 2021). "As the DUSP26 CpG island is hypermethylated in CRC, further studies might reveal that DUSP26-HSF4b interactions are tumour-suppressive in this setting." (PMID 33466673, 2021). "DUSP26 was detected in neurons and neuropil of normal brain tissue but staining was usually low or absent in tumor areas." (PMID 27586084, 2016). "The tumor suppressor activity of p38α has been studied in relation to the occurrence of the overexpression of several negative modulators of p38 MAPK signaling in various human tumor types, such as the phosphatases PPM1D and DUSP26 and ASK1 inhibitors." (PMID 35008796, 2021). "High expression of DUSP26 was detected in the neuropil and neurons in the normal brain, while expression was usually absent or low in GBM tumor tissues." (PMID 33718185, 2021). "Since normal cells within tumor microenvironment may also account toward DUSP26 expression profiling by RNA-sequencing, therefore, estimate to DUSP26 mRNA seen in GBM tissues may not be a true estimate of DUSP26 levels in GBM cells." (PMID 33718185, 2021).
cancer (8 papers, 2014 to 2021). A tumor composed of atypical neoplastic, often pleomorphic cells that invade other tissues. "The 8p region containing the DUSP26 gene is often a target of amplification or loss of heterozygosity in cancer." (PMID 33466673, 2021). "Indeed, the levels of p-FADD were high in 62% of cancers showing low levels of AK2 expression and in 75% of cancers showing DUSP26 deficiency." (PMID 24548998, 2014). "DUSP26 is known to be involved in tumorigenesis and in the progression of cancers." (PMID 27583453, 2016). "Cancer-specific alleviation of AK2 expression was observed in 13 samples (93%), including cancers in clinical phase I (four cases), II (six cases) and III (three cases) phases, out of the 14 matched tissue sets and DUSP26 expression was lost in 57% of cancers." (PMID 24548998, 2014).
DUSP26 also shares sentences with these, for which no sentence is quoted: Alzheimer disease (3 papers); Cognitive impairment (3); Parkinson disease (3); colitis (2); infection (2); neurodegenerative disease (2); acute kidney injury (1); amyloid (1); Anxiety (1); astrocytoma (1); bacterial infection (1); brain tumors (1); cervical carcinoma (1); coloboma (1); encephalomyelitis (1); Huntington disease (1); inflammation (1); liver diseases (1); malignant glioma (1); memory impairment (1); nonalcoholic steatohepatitis (1); oligodendroglioma (1); Pancreas (1); parasitic disease (1); Parkinsonism (1); tauopathy (1); Tremor (1); α-synucleinopathy (1).